TRPV1 (transient receptor potential cation channel subfamily V member 1)
Diseases named in the same sentence as TRPV1 in open-access papers (continued):
Sharing a sentence is not in itself a finding about the gene and the disease.
tauopathy (3 papers, 2024 to 2025). Neurodegenerative disorders involving deposition of abnormal tau protein isoforms (tau proteins) in neurons and glial cells in the brain. "Immunofluorescence staining revealed enlarged lateral ventricle area, increased neuronal loss, and increased tauopathy in TRPV1−/−/E4 (AAV-hTau) mice." (PMID 39468688, 2024). "Together, these results suggest associations of TRPV1 activity with microglia-dependent antigen presentation and the adaptive immune response in E4 mice with tauopathy." (PMID 39468688, 2024). "Here, we report that capsaicin administration reduced microglial cholesterol accumulation and improved cognitive function of APOE4 mice with tauopathy, while microglia‐specific TRPV1 deletion accelerated pathology in APOE4 mice with tauopathy." (PMID 39468688, 2024). "Meanwhile, the influence of TRPV1 activation on synaptic function and cognition is studied using a tauopathy mouse model." (PMID 37641913, 2024). "The data provide additional evidence to support the protective effect of capsaicin on neuronal function and cognition, and suggest that TRPV1 could be a potential disease‐modifying target for the intervention of tauopathies." (PMID 37641913, 2024). "Moreover, microglia-specific deficiency of TRPV1 gene accelerated glial inflammation, T cell response and associated neurodegeneration in an APOE4-related tauopathy mouse model." (PMID 39468688, 2024). "We identified that capsaicin could potently inhibit mTOR activity in cells and mice, supporting TRPV1 activation as a potential intervention for neuronal damage in tauopathy." (PMID 37641913, 2024). "In the present study, we aim to clarify whether and how the TRPV1 agonist capsaicin affects neuronal tau pathology, by employing cellular and animal models of tauopathy." (PMID 37641913, 2024). "Considering the presence of autophagic dysfunction in brains of tauopathy patients and the role of TRPV1 activation in modulating the autophagy pathway, we first examined changes in LC3 and p62 protein levels in mouse hippocampi to investigate whether the autophagy process is altered by capsaicin." (PMID 37641913, 2024). "Our findings reveal that capsaicin‐induced TRPV1 activation confers neuroprotection by restoring neuronal tau homeostasis via modulating cellular autophagy and provides additional evidence to support the potential of TRPV1 as a therapeutic target for tauopathies." (PMID 37641913, 2024). "TRPV1-mediated Ca2+ influx in microglia reduces cholesterol accumulation and rescues neurodegeneration in APOE4 mice with tauopathy." (PMID 39468688, 2024). "Overall, these studies demonstrated that microglia lacking TRPV1 have enhanced correlation with T cells in E4 mice with tauopathy." (PMID 39468688, 2024). "Together, these findings validated the in vivo relevance of the mechanism identified in vitro and confirmed that TRPV1 regulates microglial cholesterol metabolism and immune function, thus suggesting potential therapeutic targets to prevent APOE4-related immune response in tauopathies." (PMID 39468688, 2024).
thyroid cancer (3 papers, 2020 to 2021). "For example, CB1, CB2, and TRPV1 are highly expressed on the cell surface of the thyroid cancer cell line, SkiMol; however, inhibition of these receptors only mildly affected the anti-proliferative effect of CBD in SkiMol." (PMID 33143283, 2020). "Other investigations have indicated that the TRPV1 and TRPV6 ion channels are of importance in thyroid cancer cells." (PMID 33919125, 2021).
tongue squamous cell carcinoma (3 papers, 2022 to 2025). A squamous cell carcinoma that arises from the tongue. "In our assessment of 13 patients (10 males, 3 females) with tongue squamous cell carcinoma, intratumoral sensory nerves expressing TRPV1 and CGRP dominated and appeared to be responsible for pain transmission." (PMID 40951290, 2025).
ulcer (3 papers, 2017 to 2023). "Our study further demonstrates that F.AOH could be employed as an anti-GU plant component as it has involved in TLR4/NF-κB and TRPV1 signalling pathways and gastric mucosal ulcer healing." (PMID 36541204, 2023). "Pretreatment of TRPV1 antagonist did not change the MPO activity in tissues (n = 8, P = 0.48 vs ulcer control group), but abolished the effect of SNP." (PMID 28522805, 2017).
varicocele (3 papers, 2018 to 2024). A condition characterized by the dilated tortuous veins of the spermatic cord with a marked left-sided predominance. "For example, TRPV1 mRNA expression, a cation channel that plays a role in spermiogenesis, was found to have significantly lower expression in men with varicoceles." (PMID 38392299, 2024). "Here, a central role for TRPV1 expression in varicocele was demonstrated, even though further experimental studies are needed to better understand the function of this receptor in the etiopathogenesis of this complex disease." (PMID 30539009, 2018). "Among different components of ECS, a crucial role in varicocele seems to be exerted by TRPV1." (PMID 30539009, 2018). "According to this, the results of the present research support the idea that downregulation of testicular TRPV1 expression may deprive the testis of a protective mechanism against the detrimental milieu induced by varicocele, reducing in turn the fertility potential." (PMID 30539009, 2018). "The current study is targeted to observe the effect of differential expression of the heat-sensitive TRP channel TRPV1 in sperm on influencing fertility outcome via natural conception or conception with ART as well as in hypoxic and hyperthermic conditions (varicocele) with elevated ROS level." (PMID 36211461, 2022). "Indeed, the surgical induction of varicocele determined a significant down-regulation of TRPV1 gene expression in left testes, without affecting gene expression of any other ECS component under study." (PMID 30539009, 2018). "Incidentally, TRPV1 is a nonselective cation channel that acts as a polymodal sensor and molecular integrator of different noxious stimuli, including heat stress and oxidative stress that represent two major hallmarks of varicocele pathogenesis." (PMID 30539009, 2018).
Airway obstruction (2 papers, 2019 to 2021). Obstruction of conducting airways of the lung. "In summary, our data show that centrally administered BK activates B2 receptors which results in enhanced citric acid-induced cough and airway obstruction via the sensitization of TRPV1 and/or TRPA1 channels through metabolites of COX and/or 12-LOX." (PMID 31170972, 2019). "Our findings show that central BK administration sensitizes cough and enhances airway obstruction via a B2 receptor/TRPV1 and/or TRPA1 channels which are coupled via metabolites of COX and/or 12-LOX enzymes." (PMID 31170972, 2019). "Collectively, our findings point to an important role for BK, via B2 receptors, in the central sensitization of airway responses namely cough and airway obstruction and further identify TRPV1, TRPA1 and metabolites of COX and 12-LOX as key molecules in the sensitization process." (PMID 31170972, 2019). "Based on the fact that BK-enhanced cough and airway obstruction were dependent on both TRPV1 and TRPA1 channels activation, in our next experiments we assessed whether combined treatment with sub-maximal doses of the TPRV1 and TRPA1 antagonists would achieve greater inhibitory effects." (PMID 31170972, 2019). "An important finding in this study is that simultaneous blockade of TRPV1 and TRPA1 results in a synergistic inhibitory effect on cough and airway obstruction." (PMID 31170972, 2019). "Our next question was whether TRP channels, specifically TRPV1 and TRPA1, were involved in the BK sensitization of cough and airway obstruction." (PMID 31170972, 2019). "In addition, combined blockade of TRPV1 and TRPA1 or COX and 12-LOX resulted in a greater inhibitory effect of both cough and airway obstruction." (PMID 31170972, 2019). "Furthermore, our data show that combined blockade of both TRPV1 and TRPA1 channels results in greater degree of inhibition of both cough and airway obstruction." (PMID 31170972, 2019). "The link between TRPV1 and TRPA1 activation and increased airway obstruction is not clear, However, multimodal activation of TRPV1 channels trigger increased spontaneous glutamate release within the nTS." (PMID 31170972, 2019). "Furthermore, co-administration of submaximal doses of the TRPV1 and TRPA1 antagonists or the COX and 12-LOX inhibitors resulted in a greater inhibition of both cough reflex and airway obstruction." (PMID 31170972, 2019). "In addition to the effects on cough, our data show that blockade of both the TRPV1 and TRPA1 channels (by JNJ-17203212 and HC-030031, respectively) resulted in a significant inhibition of the BK-induced enhancement of airway obstruction by 77 and 80%, respectively." (PMID 31170972, 2019).
Arrhythmia (2 papers, 2011 to 2014). Any cardiac rhythm other than the normal sinus rhythm. "Intratracheal application of an antagonist of the vanilloid receptor TRPV1 (AMG 9810, 30 mg/kg) prevented enhancement of systolic blood pressure and arrhythmia in vivo, as well as basal and reperfusion-induced myocardial injury ex vivo." (PMID 24568236, 2014). "We hypothesized that a single exposure to wDE would sensitize the heart to aconitine-induced arrhythmia, a response that could be prevented by blocking TRPA1 (and possibly TRPV1) or by sympathetic modulation." (PMID 21377951, 2011). "In the present study, we indirectly examined the role of airway C-fibers in increasing the sensitivity of animals to aconitine-induced arrhythmia after exposure to wDE by testing the involvement of TRPA1 and TRPV1 ion channels, which are the chemical-sensing structures colocalized to these fibers." (PMID 21377951, 2011).
autoimmune hepatitis (2 papers, 2023 to 2026). Hepatitis caused by autoantibodies. "CBD also induces the suppression of autoimmune hepatitis, which was dependent on TRPV1, and inhibits the uptake of the endocannabinoid anandamide (AEA)." (PMID 38003444, 2023). "TRPV1 plays a role in immune system modulation, particularly in autoimmune hepatitis." (PMID 41569118, 2026).
Autoimmunity (2 papers, 2012 to 2025). The occurrence of an immune reaction against the organism's own cells or tissues. "For example, the M315I variant of TRPV1 has been associated with an increased risk of T1D in Ashkenazi Jewish populations, suggesting a potential genetic contribution to β-cell autoimmunity or heightened sensitivity to environmental stressors such as oxidative damage or viral exposure." (PMID 41463571, 2025). "A critical gap remains in understanding how chronic hyperglycemia, autoimmunity, and sustained inflammation alter TRPV1 expression and signaling within specific vascular territories." (PMID 41463571, 2025). "Additionally, TRPV1 appears to modulate cytokine release and immune cell activation, suggesting it may serve as a regulatory point in inflammation and autoimmunity." (PMID 41463571, 2025).
basal cell carcinoma (2 papers, 2021 to 2023). A carcinoma involving the basal cells. "In addition to SQCC, TRPV1 is highly expressed in basal cell carcinoma (BCC)." (PMID 37240443, 2023).
bladder transitional cell carcinoma (2 papers, 2013 to 2022). The most common morphologic subtype of urinary bladder carcinoma (over 90% of cases). "Capsaicin enhanced the antiproliferative effects of pirarubicin by activating TRPV1 in human bladder transitional cell carcinoma 5637 cells." (PMID 35402237, 2022). "However, it was reported that capsaicin induced cell cycle arrest and apoptosis in urothelial bladder cancer cells through TRPV1 activation." (PMID 24454492, 2013).
Brain atrophy (2 papers, 2019 to 2021). Partial or complete wasting (loss) of brain tissue that was once present. "In vivo, hampered TRPV1 function significantly reduced brain atrophy, infarct size, and the number of IL-1β-positive astrocytes in the hippocampus." (PMID 31142341, 2019). "Brain atrophy in either TRPV1 KO mice or WT capsaicin pre-treatment mice is significantly reduced." (PMID 31142341, 2019). "In addition, the brain atrophy and infarct size of TRPV1 KO mice after HI were decreased, which was found to be closely related to suppressing the activation of astrocytes and releasing astrocyte-derived IL-1β, mainly via JAK2-STAT3 signaling and activation of the NLRP3 inflammasome." (PMID 34691200, 2021).
brain inflammation (2 papers, 2012 to 2023). "The antagonistic effect of WIN on TRPV1 was also responsible for a reduction in microglia activation in a model for age-associated brain inflammation." (PMID 23139770, 2012).
breast invasive carcinoma (2 papers, 2020 to 2022). "Reportedly, TRPV1 is expressed in various human cancer tissues, with TRPV1 expression found to be associated with lower survival in invasive breast carcinoma." (PMID 32604833, 2020).
breast tumor (2 papers, 2022 to 2023). "There are significantly more sensory nerves (TRPV1+/β3-tubulin+) in breast tumor tissues than in healthy breast, with sensory nerves covering on average 2.23% of tumor area." (PMID 36333352, 2022). "Further, over 80% of patients in our dataset exhibit high level of β3-tubulin+/TRPV1+ signal, suggesting that a majority of breast tumors have sensory nerve infiltration." (PMID 36333352, 2022).
burning mouth syndrome (2 papers, 2022 to 2025). A condition characterized by a burning or tingling sensation on the lips, tongue, or entire mouth. "Patients with burning mouth syndrome (BMS) have an increase in both the presence of TRPV1+ nerve fibers and in epithelial TRPV1 expression." (PMID 36635242, 2022). "Many scholars demonstrated an increased expression of TRPV1 in patients with burning mouth syndrome (BMS), which is a common oral mucosal disease characterized by a persistent burning sensation and pain lasting for more than three months without any local or systemic pathological changes." (PMID 39859376, 2025).
cardiac arrest (2 papers, 2010 to 2011). Cessation of breathing and/or cardiac function. "The results indicate that the susceptibility of the resuscitated cardiac arrest rats towards TRPV1 agonist induced Bezold-Jarisch reflex is increased compared to the healthy situation." (PMID 20807439, 2010). "Our results indicate that the susceptibility of the rats towards TRPV1 agonist induced Bezold-Jarisch reflex is increased in those resuscitated from cardiac arrest compared to the healthy situation." (PMID 20807439, 2010). "The TRPV1 antagonist SB366791 appeared to prevent increased sensitivity to aconitine caused by low wDE based on VPB and VT, but aconitine doses required to elicit VF and cardiac arrest after wDE were comparable to those in rats without pretreatment." (PMID 21377951, 2011).
cardiomyopathies (2 papers, 2021 to 2024). "TRPV1 appears to have conflicting roles regarding the development of cardiomyopathies." (PMID 34867442, 2021).
cervical adenocarcinoma (2 papers, 2022 to 2025). An adenocarcinoma arising from the cervical epithelium. "The expression levels of TRPV, TRPC and TRPM were decreased in cervical squamous cell carcinoma and cervical adenocarcinoma, with more obvious trend of TRPV1 and TRPC1, while the expression of TRPV and TRPM increased." (PMID 36072430, 2022). "We have discovered that TRPV1 is low expressed in CSCC and cervical adenocarcinoma compared to normal group, meanwhile TRPV1 showed the lower expression level in CSCC compared to cervical adenocarcinoma group." (PMID 36072430, 2022). "The expression of TRPV1 was lower in cervical squamous cell carcinoma (CSCC) and cervical adenocarcinoma than in normal group, and lower in CSCC than in cervical adenocarcinoma group." (PMID 40007993, 2025).
complex regional pain syndrome I (2 papers, 2019 to 2022). "Enhanced expression of TRPV1 on KCs was observed in a rat cast immobilization model of complex regional pain syndrome I (CRPS I)." (PMID 36157074, 2022).
cystic fibrosis (2 papers, 2019 to 2024). Autosomal recessive disorder caused by pathogenic variants in the CFTR gene (cystic fibrosis transmembrane conductance regulator), which encodes a chloride and bicarbonate channel expressed in epithelial cells, and follow the diagnosis criteria. "In cystic fibrosis, TRPV1 activation could improve CFTR function and cough effectiveness, while β2AR stimulation increases mucociliary clearance and favors bronchodilation." (PMID 39408565, 2024). "Since the capsaicin receptor is TRPV1, it could be supposed that a different pattern of activation of this receptor in the lung sensory neurons of patients with cystic fibrosis is present, with a low range of cough sensitivity in children and not in adults." (PMID 39408565, 2024).
diabetic nephropathy (2 papers, 2023 to 2025). "Delayed renal reperfusion following ischemic injury has been linked to altered TRPV1 signaling in diabetic mice, and TRPV1 activity mediates oxidative stress–induced mesangial injury and fibrosis in diabetic nephropathy." (PMID 41463571, 2025). "Through regulating TRPV1-mediated intracellular Ca2+ homeostasis, capsaicin has been reported to exert a range of biological activities, such as antitumor activity, antagonizing diabetic nephropathy and long-lasting analgesia activity, etc.." (PMID 37446918, 2023).
disc degeneration (2 papers, 2019 to 2022). "In response to a disc injury, TrpV1 is widely activated, causing inflammatory pain and nociception, leading to potential disc degeneration." (PMID 36428977, 2022). "Further, our studies highlight association of NF-κB signaling with SP and TRPV1 expression in IVD tissues, suggesting the role of NF-κB in the pathophysiology of disc degeneration leading to chronic low back pain." (PMID 30717434, 2019).
Dravet syndrome (2 papers, 2022 to 2024). "Among the Dsm5 potential modifier genes, Trpv1 is an intriguing candidate as a proposed target of cannabidiol, an FDA/EMA-approved Dravet syndrome therapeutic." (PMID 35606653, 2022).
encephalomyelitis (2 papers, 2012 to 2025). Inflammation of the brain and the spinal cord. "TRPV1 stimulation induces IL-6 amplification and exacerbates encephalomyelitis with excessive induction of other pro-inflammatory cytokines." (PMID 40823821, 2025).
enteritis (2 papers, 2014 to 2017). Inflammation of the small intestine. "Capsaicin, the pungent ingredient in chili peppers, is an activator of TRPV1 that has been shown to cause enteritis that is very similar to that caused by toxin A in the rat ileum." (PMID 25045574, 2014). "In addition, the inflammatory effects of capsaicin and RTX in the ileum and colon are very similar to the effects of toxin A, further emphasizing the concept that endogenous TRPV1 agonists mediate some or all of the effects of Clostridium difficile toxin A on enteritis." (PMID 28484490, 2017).
esophageal squamous cell carcinoma (2 papers, 2019 to 2023). Esophageal squamous cell carcinoma (ESCC) is a type of esophageal carcinoma (EC) that can affect any part of the esophagus, but is usually located in the upper or middle third. "The protein expression of TRPV1 is upregulated in the esophageal squamous cell carcinoma (ESCC) cells, and the recurrent activations of TRPV1 promotes the migration of ECA109 cells." (PMID 38129926, 2023). "We found that TRPV‐1, 2, and 4 were all expressed at both mRNA and protein levels in the nontumor esophageal squamous cells and esophageal squamous cell carcinoma cells, whereas TRPV3 mRNA transcript and protein were not detectable among all 3 cell lines." (PMID 30761248, 2019).